CD69 (CD69 molecule)
Diseases named in the same sentence as CD69 in open-access papers (continued):
Sharing a sentence is not in itself a finding about the gene and the disease.
melanoma (continued). "Subrahmanyam and colleagues found that MIP1β+ CD69+ NK cells were significantly higher in melanoma patients responding to anti-PD-1 therapy." (PMID 33802954, 2021). "The cytokines IFN-γ and TNF-α and the expression of CD69 were evaluated after OTI TCR CD8+ T cells were incubated with OVA+-B16F10 melanoma cells." (PMID 33597944, 2020). "Since Porins facilitate formation and expansion of circulating memory cells in the SDLN, we also evaluated its capacity to induce Trm T cells (CD103+ CD69+) in the skin, perhaps the most relevant population for melanoma control." (PMID 33240271, 2020). "CD69+CD8+ memory T cells generated before melanoma inoculation play a critical role in tumor surveilance." (PMID 32161584, 2020). "The role of activated NK cells (expressing MIP-1β and CD69) in the context of anti PD-1 therapy of melanoma patients has recently been highlighted by Hodi and colleagues." (PMID 31176366, 2019). "In co-culture with two melanoma cell lines, ME4405 and SK-MEL-28 (which harbor BRAF and NRAS mutations, respectively), we observed that knockdown of CCNB1 in melanoma cells increased the proportion of NK-92MI expressing CD69 and CD107a, which are key markers of NK cell activation." (PMID 40430484, 2025). "Interestingly, CD45RO+ and EOMES+ memory T cells measured in baseline melanoma tissue also highly expressed CD69 and CD103." (PMID 38562921, 2024). "Tumor-specific epidermal CD69+ CD103+ Trm cells have a sustained protective effect on melanoma patients, especially premelanoma melanoma-specific Trm cells, which can function independently of circulation and have a far-reaching inhibitory effect on tumor development." (PMID 38779662, 2024). "Coculture with the A2+/NY+ melanoma cell line A375 revealed consistently higher upregulation of the activation markers CD69 and CD137 as well as of the inhibitory markers lymphocyte-activation gene 3 (LAG3) and programmed cell death protein 1 (PD-1) for CD8+ A97L–T cells as compared with WT." (PMID 38828721, 2024). "However, the CD8+ TIL in ADU-S100 + anti-PD-L1 vs. ADU-S100 only treated B16 melanomas expressed significantly higher levels of early activation marker CD69, consistent with their enhanced functional status, but they exhibited no significant changes in Granzyme B or PD1 expression." (PMID 38312842, 2024). "Moreover, in the same study, a greater quantity of tumor-resident CD69+CD103+CD8+ T cells was linked to better melanoma-specific survival in stage III patients not receiving adjuvant anti-PD-1." (PMID 39273452, 2024). "In addition, the numbers of CD69-positive CD8+ T cells in melanoma of NPTyr-αPD-L1, NPTyr-CXCL9 & anti-PD-L1 or NPTyr-C9AP groups respectively reached 3.71, 6.34 or 7.56 × 105 cells per gram tumor, which was 1.3-, 2.2- and 2.6- fold of that in the anti-PD-L1 group." (PMID 37031188, 2023). "The microenvironment of the harvested melanoma used to generate the TIL product contained an abundance of CD8+TCF1+ and CD8+CD69+ T cells, spatial co-clustering of CD8+ T cells with CD11c myeloid networks." (PMID 41333460, 2025). "We noted a significant elevation in CD69 and CD137 expression levels in co-culture with melanoma targets." (PMID 40181966, 2025). "In melanoma, IL-15 expression positively correlates with TRM abundance and higher mRNA levels of ITGAE (CD103), ITGA1 (CD49a), and CD69, reinforcing its role in maintaining residency and effector potential." (PMID 41479900, 2025). "CD103+CD69+ TRM cells showed a high expression profile of immune checkpoint proteins and were located within the tumor tissue of melanoma patients, suggesting them to be an ideal subpopulation of T cells to be reinvigorated by ICI." (PMID 38562921, 2024). "Increased expression of GZMB, CD69, IFN-γ, CD25 or CD107 in CD8+ T cells was detected in BRafV600E/Ptennull melanomas, and their induction was further augmented by the anti-PD-1 treatment." (PMID 38461299, 2024).
melanoma (continued). "In the mouse B16F10-Ova melanoma model, intradermal vaccination induces a stronger accumulation of CD8+CD69+CD103+ TRM cells than intraperitoneal immunization and results in stronger protective effects due to the local protective effect of TRM cells." (PMID 37545498, 2023). "The melanoma clusters were mainly distinguished by the level of expression of IFN-γ (C8), and KI-67, CD69, and PD-1 (C6)." (PMID 36902214, 2023). "Further analysis showed that in lung cancer responders, CD69 was upregulated while SBK1 was downregulated and that in melanoma responders, both were upregulated." (PMID 36045683, 2022). "Analysis of melanoma datasets (SKCM and UVM) showed that CD69 expression positively correlated with PD-1 and PD-L1 but the correlation between SBK1 and PD-1 or PD-L1 was not significant." (PMID 36045683, 2022). "In immunotherapy-naive melanoma patients, the intratumoral presence of CD8+CD103+CD69+ T cells that are able to significantly increase during anti-PD-1 therapy has been associated with improved survival." (PMID 33723257, 2021). "In contrast, CD69+ NK cells were shown to negatively correlate in melanoma patients with progression-free survival (PFS) less than 6 months, while CD69+ NK cells were positively correlated with PFS in melanoma patients with PFS greater than 6 months." (PMID 33802954, 2021). "As determined by mass cytometry of melanoma tissues using a panel of 43 markers, CD8+/CD4+EOMES+CD69+CD45RO+ effector memory T cells were significantly more abundant in responders of combined immunotherapy compared with non-responders." (PMID 34360781, 2021). "There were modest differences, which included an increase in CD69 and decreased CD62L expression by all ILC subsets in melanoma patients." (PMID 33810032, 2021). "A previous study has shown that CD56dim CD57lo CD69+ CCR7+ KIR+ NK cells expand in tumor-infiltrated lymph nodes and display enhanced cytotoxic activity against autologous melanoma cells." (PMID 30761123, 2019). "Human melanoma cells (A375M) served as a positive control for the stimulation of CSPG4-CAR T cells and correspondingly induced upregulation of CD25 and CD69 expression on CSPG4-CAR T cells." (PMID 31195686, 2019). "Within human melanoma tumors, VLA-1 was frequently expressed in combination with both CD69 and CD103, the archetypal markers for TRM differentiation, as has been reported on virus-specific TRM from murine skin and brain." (PMID 28018343, 2016). "Also, topical administration resulted in an increased expression of some markers for NK cell activation and maturation, such as CD69, NKp46, CD122, CD11b, CD43, KLRG1, and CD27, when compared with melanoma-bearing mice." (PMID 41597427, 2026). "One study demonstrated that tumor DNA priming immunization followed by an intranasal live-attenuated influenza boost can reprogram TCM cells into CD103+CD69+ TRM cells within two days of mucosal boosting, providing robust protection against melanoma and mesothelioma lung metastases in mice." (PMID 40862776, 2025). "Functional studies in murine models of LCMV infection and melanoma demonstrated that deletion of Runx3 results in a dramatic reduction, ranging from 50- to 150-fold in CD8+ T cells expressing CD69 and CD103 across various tissues, including salivary glands, kidneys, skin, and lungs." (PMID 41479900, 2025). "Moreover, an increase of GZMB expression and upregulation of CD8+ T-cell activation markers, such as CD69, IFN-γ, CD25 and CD107, were detected in BRafV600E/Ptennull/Mi-2βnull melanomas after Mi-2β knockout." (PMID 38461299, 2024). "In the TIL compartment, B16 melanomas treated with ADU-S100 + anti-ISG15 (vs. ADU-S100 alone) displayed a significant decrease in total CD8+ TIL content, but these T cells were enriched in the CD8+CD69+ activated phenotype." (PMID 38312842, 2024).
melanoma (continued). "ROC analysis revealed that AUC values for the ability of CD69, SBK1 and RN7SK to predict response to PD-1/PD-L1 blockade immunotherapy in lung cancer were 0.754, 0.803, and 0.797, respectively, while in melanoma they were 0.637, 0.668, and 0.597, respectively." (PMID 36045683, 2022). "Re‐stimulation of splenocytes isolated from these mice with B16F10 melanoma cells revealed a significant increase of the early activation marker CD69 in CD8+ but not in CD4+ T‐cells." (PMID 32440479, 2020). "NK cells isolated from PBMCs and subsequently treated with HSVGM-CSF directly were unable to degranulate against melanoma targets and showed no upregulation of the early activation marker CD69." (PMID 31053413, 2019). "Moreover, VLA-1+ CD8 T cells were strongly enriched in melanoma metastases (lung, skin and brain) and displayed a Trm phenotype expressing the CD103 and CD69 surface markers." (PMID 30258445, 2018). "Therefore, we tested the ability of CD69 and CD103 to characterise the TRM subset in melanoma." (PMID 40985995, 2025). "Indeed, TRM cells (CD8+/CD103+/CD69+/CD44+) in normal skin lack immune checkpoints and are critical for protection against melanoma by eliminating major histocompatibility complex (MHC) class I positive melanoma cells." (PMID 37334356, 2023). "Characterization of CD4+ T cell residency was based on CD69+ expression, finding that the majority of CD4+ T cells in primary melanoma are not tumor-resident (CD69+ = 26.5%, CD69- = 72.27%, p = 0.0022)." (PMID 36003398, 2022). "To ensure that the observed reduction in CD69 and CD86 expression was not due to effects of CK-666 on the APCs, we used Arp3 siRNA to deplete the Arp2/3 complex in B16F1 murine melanoma cells expressing the single chain anti-Igκ Ag." (PMID 31157616, 2019). "Analyzing the expression of the early activation marker of T‐cells, CD69, a significant increase was observed for the Ar/O2, He, and He/O2 conditions when comparing splenic CD4+ T‐cells cultured in the presence or absence of melanoma cells." (PMID 32440479, 2020). "Additionally, a tendency toward lower CD31 (p = 0.09) and CCR3 expression (p = 0.10), and higher CD69 (p = 0.07) and CD29 expression (p = 0.15) was observed on neutrophils from late-stage melanoma patients compared to healthy donors, which were all not statistically significant." (PMID 38730718, 2024). "Notably, in 5/12 melanoma patients, non-MTEX also mediated CD69 downregulation on T cells." (PMID 31919420, 2020).
influenza (55 papers, 2009 to 2025). An acute viral infection of the respiratory tract, occurring in isolated cases, in epidemics, or in pandemics; it is caused by serologically different strains of viruses (influenzaviruses) designated A, B, and C, has a 3-day incubation period, and usually lasts for 3 to 10 days. "While a CCR2 deficiency led to attenuated percentages of tipDCs in influenza-infected mice compared to controls, as previously reported, percentages of CD69+, CD4 and CD8 T cells were significantly attenuated in CCR2 deficient mice." (PMID 20967263, 2010). "Interestingly, the authors reported that lung CD8+ TM are very susceptible to age-associated attrition and showed that CD8+ CD103+ CD69+ TRM influenza-specific cells declined with age while CD8+ CD69- CD103- T frequencies increases." (PMID 33874975, 2021). "Interestingly, influenza infection with seasonal strains was associated with significantly higher proportions and higher absolute numbers of CD69+ NK cells compared to swine influenza infection (p = 0.002 and p = 0.009, respectively)." (PMID 21966414, 2011). "A more detailed characterization of these lung TRM cells also show that intranasal influenza is unique in promoting upregulation of CD69 and CD103, in comparison to intranasal LCMV." (PMID 38375476, 2024). "Flow cytometry analysis revealed reduced numbers of CD8+ CD69+ CD103+ resident T cells in the lungs of alcohol consuming influenza infected mice in comparison to water-fed control mice." (PMID 37485352, 2023). "In contrast, CD69 upregulation was overall higher and more uniform between the T cell subsets in influenza." (PMID 35371005, 2022). "In contrast, a high percentage of CD69+ lymphocytes is observed in pregnant patients with AH1N1 influenza, another respiratory virus challenge that leads to unregulated inflammation in the lungs." (PMID 35901034, 2022). "A high proportion of NP specific T cells in TBLN expresses CD69 from 6 days after influenza challenge until 63 DPI perhaps representing either continuing antigenic stimulation or recirculation of TRM10." (PMID 35145208, 2022). "Fewer CD69+granzyme+ cytotoxic T cells and CD69+IFN-γ+ Th cells are found in obese individuals receiving influenza immunizations compared with lean controls." (PMID 33724954, 2021). "A study of influenza infection in mice demonstrated influenza-specific lung-resident memory T cells were CD69+, with CD4+ TRM cells co-expressing CD11a and CD8+ TRM cells co-expressing CD103." (PMID 32974217, 2020). "Our transcriptional analysis revealed selective upregulation of the IL-2 receptor alpha chain (Il2ra) by CD69+ CD8+ TRM cells arising in the lungs after influenza infection, potentially indicating increased responsiveness to IL-2." (PMID 30899267, 2019). "To examine the ability of NKT cells to produce these molecules, we first assessed their kinetics of activation after influenza infection by measuring the levels of the surface activation marker CD69." (PMID 29249358, 2018). "Compared to controls, animals immunized to A/NP+M2 had more influenza-specific cells expressing the early activation marker CD69." (PMID 27055234, 2016). "In the DLNs, CD69 expression was differentially upregulated in CD8 cells after CpG + Inact or influenza immunization while only PR8 infection resulted in increases in CD4 cells." (PMID 26161083, 2015). "We observed an increased proportion of CD69+ cells only in the T lymphocytes in H1N1pdm2009 virus-infected pregnant women compared with influenza-like illness-infected pregnant women." (PMID 25254368, 2014). "This provides evidence that the in vivo up-regulation of CD69 induced by trivalent influenza vaccine is mediated by IFN-I." (PMID 21998693, 2011). "NK cells exposed to influenza antigens were activated, with higher proportions of NK cells expressing CD69 in study subjects infected with seasonal influenza strains." (PMID 21966414, 2011).
influenza (continued). "In order to further assess NK cell activation in influenza infection and vaccination, we looked at the expression of CD69 and CD25 at the surface of NK cells and quantified NK cell function in response to H1N1 or 221 and K562 target cells ex vivo." (PMID 21966414, 2011). "Despite this, surface expression of CD69 was detected by day 3 in adults and day 5 in aged mice, which coincided with an earlier detection of anti-influenza neutralizing antibodies in adult mice compared to aged mice." (PMID 19922665, 2009). "Both mouse-adapted influenza and coronavirus infections induce CD69 in EC of the lung." (PMID 40617350, 2025). "In mice, intramuscular immunization with an mRNA vaccine against influenza has recently been shown to elicit CD69+ and CD69+CD103+ TRM cells in the lung, which could be further boosted by intra-nasal immunization." (PMID 37019909, 2023). "Similarly, in an influenza infection model, alcohol-fed mice exhibited decreased homing to lungs, reduced CD69, CD103, and CXCR3 positive tissue resident CD8+ T cells." (PMID 37485352, 2023). "Furthermore, we investigated the presence of TRM T cell responses to influenza, using the extracellular markers CD69, CD103, and CD49a." (PMID 33497364, 2021). "However, it has been shown that γδ T cells express CD69 after recognition of influenza‐infected cells." (PMID 31777067, 2020). "However, human lung-resident CD56brightCD49a+CD69+CD103+ NK cells are potent IFN-γ producers in response to influenza infection." (PMID 32974217, 2020). "Interestingly, percentages of peripheral blood CD69+ NK cells significantly differ between patients infected with seasonal influenza strains and subjects with acute swine influenza infection." (PMID 21966414, 2011). "Furthermore, the percentage of activated (CD69+) influenza-specific and IL-2 producer CD8+ T-cells was higher in adult mice compared to aged ones." (PMID 19922665, 2009). "Confirming previous findings, intraperitoneal influenza, despite failing to promote the numerical accumulation of lung TRM cells, was sufficient to induce a consistent upregulation of CD69 and CD103 in a small proportion of lung TRM cells." (PMID 38375476, 2024). "Most of these cells expressed CD69, a marker of lung CD4+ TRM following influenza infection, resulting in a 50-100-fold increase in CD4+ TRM following heterologous rechallenge of rGP- or LCMV-derived CD4+ memory T cells." (PMID 39283916, 2024). "Next, we assessed how the expression of CD49a, CD69, and CD103 changed after a second influenza infection." (PMID 38675801, 2024). "Similar to our findings, in aged mice infected with influenza, cytotoxic CD8+CD69+ TRM cells accumulated up to 60 d postprimary infection and caused significant lung inflammation and fibrosis." (PMID 37261717, 2023). "Expression of the CD69 activation marker was evaluated on CD4+ and CD8+ cells following incubation with the influenza vaccine antigens to demonstrate immunological sensitization previously acquired in vivo by the tested individual through vaccination." (PMID 31600331, 2019). "An increase in frequency of CD154+CD69+CD45RO+CD38+ islet beta cell antigen specific CD4+ T cells was observed in subjects #1 and #2 14 days after influenza vaccination." (PMID 30619245, 2018). "For example, IFN-α and IFN-β produced by pDC have been shown to increase CD69 expression and IFN-γ production from CD4+ T cells, and also activate CD8+ T cells upon influenza challenge." (PMID 23815813, 2013). "Both in influenza- and in PVM-infected mice, BAL NK cells displayed an activated phenotype (high CD69) and produced IFNγ upon stimulation ex vivo, indicating that they were functional." (PMID 22940382, 2012). "In order to further determine the NK cell response to influenza, we assessed the expression of the activation markers CD69 and CD25 (the α-chain of the IL-2 receptor) on NK cells from patients infected or vaccinated with influenza." (PMID 21966414, 2011).